AFP (alpha fetoprotein)
Diseases named in the same sentence as AFP in open-access papers (continued):
Sharing a sentence is not in itself a finding about the gene and the disease.
tumor (continued). "The T-cell immune responses in early-stage HCC patients show diversity, while those with advanced-stage HCC predominantly display AFP-specific T-cell immune responses and few other T-cells that cannot recognize tumour cells as a result of tumour evolution." (PMID 34496797, 2021). "On subgroup analyses, the one-year OS rates were significantly different according to the median tumor size (≥5 vs. <5 cm: 62.4% vs. 82.8%; p = 0.036) and the AFP level (the median or 50% of patients ≥400 vs. <400 ng/mL: 40.5% vs. 71.7%; p < 0.001)." (PMID 34684036, 2021). "Incorporating tumor diameter, AFP and TB, the nomogram achieved a better concordance index of 0.725 (95%CI: 0.661–0.788) with 1000 bootstrap samples to measure discrimination in predicting MVI presence." (PMID 34234239, 2021). "In our study, tumor size, tumor number, tumor type, AFP level, Child–Pugh score, and NLR were incorporated into a 12-point risk prediction model." (PMID 34204125, 2021). "The pre-transplant model (Pre-MORAL) identified neutrophil to lymphocyte ratio (NLR), AFP and tumor size as independent predictors of recurrence." (PMID 34295467, 2021). "In an attempt to compensate for such a loss, the circulating levels of three tumor markers, CEA, AFP, and CA19-9, were examined." (PMID 33977101, 2021). "It has been demonstrated that AFP is effective for drug delivery, but AFP, especially tumor-derived AFP (tAFP), is also immunosuppressive and thus can stimulate immune escape of cancer cells." (PMID 33898423, 2021). "Of all the variables, the tumour margin was ranked first and was the only radiological feature ranking in the top 15 features, and α-fetoprotein (AFP) level was ranked 4th and was the only baseline characteristic ranking in the top 15 features." (PMID 32852634, 2021). "In multivariate analysis, tumor length ≥ 10 cm and AFP ≥ 200 ng/ml were independent poor prognostic factors for OS." (PMID 34336647, 2021). "The high expression of ZCCHC17 is related to AFP, histologic grade, tumor status, vascular invasion, and pathological stage." (PMID 35071004, 2021). "Another patient with a maximum tumor diameter of 12 cm, AFP level of 18 ng/mL, and PIVKA-II 19 mAU/mL died 1.2 years after LT without recurrence until death." (PMID 33996606, 2021). "Because serum AFP levels can reduce after effective treatment, it is of clinical value to measure serum AFP levels during patient follow-up or to detect tumor recurrence after treatment." (PMID 33607799, 2021). "Several clinical and pathological characteristics have been identified as predictors of tumor recurrence after HR, such as vascular tumor invasion, number and size of HCC nodules, alpha-fetoprotein level and tumor histological grading." (PMID 33572904, 2021). "In multivariate analysis, tumor size, AFP > 400 ng/mL, and ALBI-grade migration to grade 3 were independent risk factors associated with poor PFS in individual model." (PMID 34503135, 2021). "We further assessed the association of RAP genes with clinicopathological including pathological age, gender, stage, tumor grade, blood AFP levels." (PMID 34235179, 2021). "The recently developed metroticket 2.0 model considers AFP as a continuous variable, and its variations along with tumor morphology can be used as an accurate predictor of tumor-related death after liver transplantation." (PMID 34638365, 2021). "Vessels that encapsulate tumor clusters (VETC), previously linked to HCC metastatic dissemination, which was associated with high AFP levels and poor differentiation, and VETC was well correlated with MVI24." (PMID 34234239, 2021). "Marital status, age, race, histological grade of differentiation, tumor size, T stage, and serum alpha-fetoprotein levels at the time of diagnosis were identified as prognostic factors for OS and CSS." (PMID 34187430, 2021). "Apart from tumor morphology, serum AFP is another well-established predictor, with several studies highlighting the importance of this marker among patients with HCC." (PMID 33670174, 2021).
tumor (continued). "One week after the complete resection of the tumor in the second-stage operation, the alpha-fetoprotein levels of the three patients were further decreased, and return to normal." (PMID 33632257, 2021). "Periodic imaging and the determination of tumor markers (alpha-fetoprotein [AFP], human chorionic gonadotropin [HCG], and lactate dehydrogenase [LDH]) showed no recurrence or metastasis during the 5 years postoperatively." (PMID 33541424, 2021). "As expected, the residual cells from the tumor piece consisted of AFP-positive cells, which were localized with the highest concentration to the contact area of the tumor and topographic surface." (PMID 34947582, 2021). "AFP has also been suggested as a predictor for the successful downstaging of tumours prior to transplant, although a threshold has yet to be established, thus requiring further investigation." (PMID 33440759, 2021). "Univariable analyses indicated that the mean tumour size, the tumour number, AFP > 400 ng/mL, the BCLC stage and TACE + eRFA were correlated with the TTP." (PMID 33879085, 2021). "The cells were stained for α-SMA, a biomarker for activated fibroblasts such as myofibroblasts and CAFs, DAPI for the nucleus, and alpha-fetoprotein (AFP) for tumor cells." (PMID 34947582, 2021). "TB, ALT and PT had statistical significance in univariate analysis (P < 0.05), whereas the P value of the Child–Pugh score, Hb, WBC, AST, Plt, Alb, Serum AFP > 400 ng/mL, tumor size, TACE+ in univariate analysis was less than 0.001." (PMID 33436856, 2021). "Other significant variables were neutrophil count, lymphocyte count, aspartate aminotransferase, AFP, tumor diameter, tumor number, MVI, and satellite nodules." (PMID 33680963, 2021). "Improving liver functions (ALT, albumin, T bilirubin, D bilirubin, and Alfa Fetoprotein AFP) and liver microstructure characteristics of precancerous lesion rats, and improving the acidic tumor microenvironment." (PMID 33869059, 2021). "As it is technically difficult to monitor tumor volume over time in such an orthotopic model, plasma human alpha fetoprotein (AFP) was used as a surrogate measure of liver tumor development." (PMID 33747358, 2021). "As expected, the AFP score > 2 on explant was predictive of tumor recurrence (in univariate and in multivariate analysis) and was the unique predictor of post-transplant death." (PMID 34069594, 2021). "Statistically significant increases in MTD, AFP levels, tumor number and percent of patients with macroscopic PVT were found with each increase in GGT level." (PMID 34540270, 2021). "Patients were divided into two risk groups according to the prognostic score constructed with ALBI score, tumor size, tumor-invaded liver segments, gamma-glutamyl transpeptidase, alpha fetoprotein, and portal vein tumor thrombus stage." (PMID 33718130, 2021). "Robert and coworkers detected that the AFP promoter was in lower methylation in AFP-high tumors compared with the non-tumor-adjacent tissues and low-AFP-expression tumors." (PMID 34680245, 2021). "Currently, the uptake of contrast agent in the arterial phase of dynamic CT or MRI, is the reference method to assess the persistence of viable tumor in the lesion, while serum biomarkers, such as AFP and PIVKA-II, can integrate the evaluation." (PMID 33922938, 2021). "Routine blood, blood biochemistry, tumour biomarkers (AFP, CEA, CA12-5, and CA199), other blood tests and urine analysis were normal." (PMID 34217200, 2021). "Elevated tumor markers were observed in a number of patients; Elevated alpha fetoprotein levels in a HMH patient and an increased cancer antigen 125 (CA125) level was found in a patient with UESL." (PMID 34162402, 2021). "Serum small EV‐derived MALAT1, DLEU2, HOTTIP, and SNHG1 were significantly highly expressed in patients with HCC and showed good to excellent discriminating capacity that was significantly higher than that of the traditional tumor marker AFP." (PMID 34185961, 2021).
tumor (continued). "More importantly, in patients with tumor recurrence, there were 35.7% (15/42) patients in group 1 and 27.1% (16/59) patients in group 2 showed AFP levels < 10 ng/mL, respectively." (PMID 34649509, 2021). "Previous studies reported that AFP exerts its tumor promotion through interacting with PTEN, MMP9, and caspase-3 and blocking their functions on the PI3K/AKT, metastasis and caspase signaling." (PMID 33794968, 2021). "Our tree model identified 5 nodes that sub-classified the TGR by AFP, initial tumor size, and albumin." (PMID 34966854, 2021). "The group with the reduced postoperative G8 score had a greater median serum AFP concentration and a larger tumor size." (PMID 33671388, 2021). "An example of a vaccine-driven cancer therapy is the use of a recombinant tumor lysate, Hep G2 cell line lysate, to target alpha-fetoprotein (αFP)." (PMID 34696292, 2021). "The expression of EEF1E1 was positively correlated with body weight, BMI, tumor status, vascular invasion, AFP, logistic grade, T stage and pathological stage." (PMID 34282404, 2021). "Patients with aHCC in the sorafenib (n = 48) and B-HAIC (n = 48) groups were comparable in terms of age, sex, preceding treatment ratio, tumor markers such as alpha fetoprotein (AFP) and DCP, and number of intrahepatic HCCs." (PMID 33562238, 2021). "Further analyses demonstrated associations among tumor size, tumor-node-metastasis (TNM) stage, AFP level, hepatitis B surface antigen status, degree of differentiation, and FOXO6 expression." (PMID 34123834, 2021). "Tumor relapse from intrahepatic metastasis or multicentric origin is accompanied by inconsistent serum AFP." (PMID 35127471, 2021). "Clinically, PVTT is associated with large tumor size, increased tumor number, higher tumor grade, worse Child-Pugh class and higher serum alpha-fetoprotein (AFP)." (PMID 33685417, 2021). "Their sociodemographic and laboratory information, including serum tumor markers such as AFP, CEA, CA19-9, CA72-4, Cyfra21-1 and NSE were collected." (PMID 34109127, 2021). "AFP (α-fetoprotein) is the most commonly used serum tumour marker for the diagnosis of HCC, but a retrospective study shows that the sensitivity of AFP in clinical practice is only approximately 60%, while its specificity is 80%." (PMID 33858382, 2021). "The proposed system was used for detecting tumor biomarkers such as alpha fetoprotein (AFP) and carcinoembryonic antigen (CEA) and the bacterial infection biomarker procalcitonin (PCT) in serum samples and in whole blood." (PMID 34065971, 2021). "Routine blood, blood biochemistry, tumour biomarkers (AFP, CA199, and CA12-5), other blood tests and urine analysis were normal." (PMID 34217200, 2021). "Additional controversy regarding specific methods for BWSp tumor screening also exist, with differing opinions regarding use of AFP screening for HB." (PMID 34828445, 2021). "A low AFP level allows expansion on tumor size and number beyond traditional criteria with comparable outcomes." (PMID 34295467, 2021). "Our data revealed that HBV-DNA, GGT levels, AFP levels, tumor size, tumor differentiation, MVI, satellite nodules, and blood loss were associated with PHER." (PMID 33726693, 2021). "At present, AFP remains a widely used tumor-specific serological biomarker in the diagnosis and management of HCC." (PMID 34834495, 2021). "Risk factors for HCC vascular invasion include HBV infection, tumour size, multifocal localization, α-fetoprotein (AFP), γ-glutamyl transferase (GGT), alanine transaminase (ALT), etc.." (PMID 34583704, 2021). "ROC analysis and study of correlations give reasons to expect highly effective results from using tumor markers in combination with AFP and with each other." (PMID 34513063, 2021).
tumor (continued). "In clinical practice, clinicians rely on tumor number, tumor size and macro-vascular invasion in addition to several biomarkers such as AFP, CEA and CK19 to predict HCC prognosis." (PMID 34834430, 2021). "The complete response rates were also significantly different according to the median tumor size (≥5 vs. <5 cm: 11.7% vs. 37.7%; p < 0.001) and the AFP level (≥400 vs. <400 ng/mL: 5.7% vs. 21.9%; p = 0.004)." (PMID 34684036, 2021). "Incorporating three variables, tumor diameter, AFP and TB, screened through multivariate logistic regression, we built and validated a new preoperative prediction nomogram model for MVI in HCC patients." (PMID 34234239, 2021). "There were also evaluated such indices as diagnostic sensitivity, specificity, positive predictive value, negative predictive value, likelihood ratio of a positive test, the possible correlation between alpha-fetoprotein and other tumor markers." (PMID 34513063, 2021). "The combination of AFP serum levels and morphologic characteristics of the tumor also inspired European authors to expand the MC for selecting patients with HCC for LT." (PMID 34501381, 2021). "These patients also had higher odds of receiving any treatment for HCC, independent of their model for end-stage liver disease (MELD) score, serum AFP, and tumor stage." (PMID 34638333, 2021). "Our results revealed those patients with older age at diagnosis (>60) and elevated tumor markers (CA19-9, CA12-5, and AFP) had a higher proportion of the INPS High Risk group (score 5-6)." (PMID 34195071, 2021). "Univariable analyses showed that the mean tumour size, alpha-fetoprotein (AFP) > 400 ng/mL, the Child–Pugh score, the BCLC stage and the therapy method were correlated with OS." (PMID 33879085, 2021). "In both cohorts, the serum AFP levels and tumor grade were significantly higher in high Ki-67 expression group than that in low Ki-67 expression group." (PMID 34130644, 2021). "The patient follow-up consists in regular clinical evaluations (neurologic, endocrine, visual, and hearing assessments), tumour markers (serum and/or CSF AFP and β-HCG), and MRI scans." (PMID 34357128, 2021). "There was a significant, 3-fold difference in survival between these 2 groups of low-AFP patients, as well as significant differences in tumor characteristics." (PMID 34540270, 2021). "In vivo, after orthotopic implantation of tumor tissue in nude mice, serum AFP levels were 246 ± 66 μg/L for MHCC97-H with high metastatic potential and 91 ± 66 μg/L for MHCC97-L with low metastatic potential (p < 0.01, t test)." (PMID 34680245, 2021). "The patient’s levels of the tumor markers alpha-fetoprotein (AFP) and protein induced by vitamin K absence or antagonist-II (PIVKA-II) were within the normal ranges." (PMID 33555457, 2021). "High PARD3 expression was associated with advanced T stage, pathologic stage, residual tumor, histologic grade, vascular invasion and higher alpha fetoprotein (AFP)." (PMID 34040099, 2021). "The mean (SD) tumor size was 5.4 (2.6) cm, and the median preoperative serum AFP value was 73.0 ng/mL (IQR, 4.2-798.3 ng/mL)." (PMID 34609494, 2021). "The univariate analysis identified tumor size, portal vein invasion, hepatic vein invasion, extrahepatic spread, AFP, AST, albumin, NLR, and PLR as potential prognostic factors for PFS." (PMID 34124139, 2021). "The factors associated with the PFS, TTP, and OS in the univariable analyses were tumor diameter > 3.75 cm, AFP > 400 ng/ml, dose of regorafenib, and best response to regorafenib." (PMID 34670512, 2021). "Although AFP is the most widely used tumor marker for HCC, only half of all tumors secrete this protein." (PMID 33754656, 2021). "Although serum AFP levels were not available from pre- or perioperative period, this patient was followed up with serum AFP after postsurgical pathological examination demonstrated that the tumor cells were immunohistochemically positive for AFP." (PMID 34977100, 2021).
tumor (continued). "The results of univariate Cox regression analysis showed that WAC-AS1 expression(P=0.004), AFP levels(P=0.002), tumor diameter (P=0.031), clinical stage (P<0.001), PVTT (P=0.009) and Lymphatic invasion (P<0.001) are correlated with prognosis." (PMID 34527595, 2021). "With regard to prognosis, AFP ≥20 μg/L, multiple tumor, and MVI were independent risk factors for OS and tumor recurrence." (PMID 34658153, 2021). "One study has reported that inoculation of the placental carcinoembryonic-derived proteins, AFP and AFPR, causes MDSCs to become exhausted, resulting in the elimination of maternal-fetal and host-tumor immune tolerance." (PMID 33898423, 2021). "Cox proportional hazards regression analysis indicated that AFP level, TNM staging, tumour size and ACLY expression level were independent risk factors affecting the overall survival rate of HCC patients." (PMID 33393219, 2021). "In this study, we reported significant independent risk factors for recurrence of NBNC-HCC, which included large tumor diameter, multiple tumor number, elevated AFP levels, elevated NLR, and presence of MVI." (PMID 33680963, 2021). "CEA and AFP are the major tumor biomarkers that previously demonstrated the HCC-bearing rats were found to have increased levels of these serum tumor markers." (PMID 34866538, 2021). "For tumor biology, AFP was significantly higher in the Low PNI group than the High PNI group (p = 0.05)." (PMID 33129309, 2020). "The levels of other tumor markers, including alpha-fetoprotein (AFP), CA199, CA125, and carcinoembryonic antigen (CEA), were not elevated." (PMID 33019452, 2020). "In conclusion, we have selected a TCR with a balance of affinity, function, and safety profile, bearing properties that are expected to allow AFP TCR redirected T cells to specifically differentiate between AFP levels on tumor and normal tissues." (PMID 32425926, 2020). "The prognostic model in our study evaluated and included seven factors, in which tumor size reflects tumor burden, microvascular invasion, Ki67 (%) level, and tumor differentiation, which are pathologic phenotypes, and AFP and CA125 are serum biomarkers." (PMID 33312945, 2020). "According to these results, an upper limit of tumor burden was identified based on four incremental combinations of morphology and AFP values." (PMID 32075133, 2020). "High ATAD2 expression was positively related to tumor size, metastasis, serum AFP concentration, and TNM stage in our study." (PMID 32462022, 2020). "The most common risk factors for HCC recurrence after liver transplantation were tumor size and tumors, tumor differentiation, tumor markers included AFP or PIVKA-II, vascular invasion, and neutrophil-lymphocyte ratio." (PMID 33718110, 2020). "Other than tumor size and number; certain factors like AFP level, microvascular invasion (MVI) and poor grade have a significant impact on post transplant recurrence." (PMID 32787864, 2020). "The study also showed that AFP-positive was associated with less differentiated tumors, more advanced TNM stage, larger tumor sizes, and inferior survival compared with AFP-negative." (PMID 32426269, 2020). "The results of univariate Cox regression analyses showed that hepatic ALT, AST, GGT, Child–Pugh class, WBC, Cr, AFP, tumor number ≥3, and largest tumor diameter ≥5 cm obtained from the derivation cohort were predictive factors for survival." (PMID 32149077, 2020). "Univariate analysis showed that GSTA1, AFP, tumor number, tumor size, PVTT, and TNM stage were related to OS and DFS in HCC patients." (PMID 31892975, 2020). "The nomogram was developed based on tumor size, subcapsular, α‐fetoprotein (AFP), and international normalized ratio (INR)." (PMID 32702175, 2020). "By further compared the glycopeptide ratios of tumor/paracancer between low and high AFP groups, we identified 82 differently expressed glycopeptides (7.4%) between low and high AFP of HCC tumors." (PMID 32426269, 2020).